KIF3B (kinesin family member 3B)
Diseases named in the same sentence as KIF3B in open-access papers (continued):
Sharing a sentence is not in itself a finding about the gene and the disease.
cancer (13 papers, 2013 to 2025). A tumor composed of atypical neoplastic, often pleomorphic cells that invade other tissues. "In the past few years, a large body of data has shown the association of KIF3B abnormality with tumor proliferation or invasion in several human cancers." (PMID 33542902, 2020). "We further leverage this integrative data to uncover expressed mutations in several known cancer genes as well as a recurrent mutation in the motor domain of KIF3B that significantly affects kinesin–microtubule interactions." (PMID 27723755, 2016). "In addition to discovering clinically relevant alterations in known cancer genes, we observed an expressed arginine-to-tryptophan mutation in KIF3B (R293W), a type II kinesin motor protein." (PMID 27723755, 2016). "Pearson's analysis was used to determine the correlation between miR-127-3p and KIF3B mRNA in cancer tissues." (PMID 41158092, 2025). "In recent years, several studies have identified the role of KIFs (KIF3A and KIF3B) in human cancers, confirming the effect of kinesin on the proliferation or invasion of tumor cells." (PMID 33150178, 2020). "KIF3B consists of a group of molecular motors and function in vesicle transport, spermatogenesis, mitotic progression, and intravasation of cancer cells for metastasis." (PMID 33542902, 2020). "This is consistent with our finding that inhibiting KIF3B expression efficiently inhibits these processes and blocks cancer cell metastasis." (PMID 31225451, 2018). "This is consistent with our finding that targeting Kif3b expression efficiently inhibits these processes, blocking cancer cell metastasis." (PMID 29904055, 2018). "Both shRNAs targeting Kif3b protein expression showed very similar effect on HEp3 cancer cell interaction with the vasculature and collagen fiber network." (PMID 29904055, 2018). "Accordingly, when KIF3B mutant HEp3, HT1080, and MDA231 cancer cells were tested in a 3D collagen invasion assay, invasion of the KIF3B mutant cell lines was significantly reduced." (PMID 29904055, 2018). "Cancer-associated genes of the locus include ASXL1, DNMT3B, BCL2L1, TPX2, KIF3B and POFUT1." (PMID 34577783, 2021). "Therefore, KIF3B is a novel therapeutic target to block cancer metastasis and inhibit cancer development." (PMID 33542902, 2020). "Recently, the role of KIF3B in cancer progression has been widely studied." (PMID 33542902, 2020). "Silencing of Kif3b efficiently blocked in vitro cell migration in all of the cancer cell lines." (PMID 29904055, 2018). "Some of the amplified genes are rarely over-expressed at the mRNA level, while others, such as ASXL1, KIF3B and POFUT1, are over-expressed in most amplified cancers." (PMID 34577783, 2021). "Identification of KIF3B as a top metastasis target is intriguing since this gene is part of the kinesin motor machinery responsible for transporting multiple therapeutically relevant molecules such as β-catenin and MT1-MMP to the cancer cell front." (PMID 31225451, 2018). "In addtition, KIF3B and ASXL1 alsohave the potential to participatein human cancer." (PMID 29108255, 2017). "Furthermore, we identified cancer-related genes aberrantly expressed in ccRCC (BRMS1L, CPEB3, DNAJB9, KIF3B, NFIB, PTPRJ, RBL2) and targeted by members of the miR-106b-25 cluster, suggesting that their dysregulation may be driven by these miRNAs." (PMID 40943553, 2025). "Moreover, patients with recurrent carcinoma showed higher expression of KIF3B than those without recurrence (P < 0.01)." (PMID 33542902, 2020). "Moreover, a detailed survey of immunohistochemical staining of human cancers indicated that SRPK1, KIF3B, C14orf142, NR2F1, and TMEM229B have significantly increased expression in the invasive zone of the primary tumors of these cancers as delineated by a pathologist." (PMID 29904055, 2018).
tumor (11 papers, 2014 to 2025). "Overall, KIF3B harbored verified nonsynonymous mutations in ∼6% of the tumor samples, and the R293W mutation was observed in a second independent patient." (PMID 27723755, 2016). "Applying Simul-seq to laser-capture-microdissected tumor tissue revealed a highly aneuploid somatic landscape, including a recurrent R293W mutation in KIF3B that dramatically reduced kinesin–microtubule interaction." (PMID 27723755, 2016). "KIF3B has been linked to the intracellular trafficking of several tumor suppressor genes, and biochemical data have shown that substitution of specific arginine and lysine residues within the kinesin motor domain negatively impacts kinesin-microtubule association." (PMID 27723755, 2016). "Collagen fibers at the Kif3b mutant tumor fronts appeared to be disorganized with an almost complete absence of collagen bundles." (PMID 29904055, 2018). "Moreover, patients with lower expression of KIF3B correlated with fewer residual tumor and better survival rate, thus indicating YY1 influenced the radiosensitivity of ESCC through regulation of KIF3B." (PMID 38065955, 2023). "Considering that dysregulation of mitotic progression could lead to abnormal proliferation of tumor cells, the role of KIF3B in tumor evolution has been studied widely." (PMID 38065955, 2023). "We next explored the tumor-forming capacity of KIF3B-silencing MDA-MB-231 cells in nude mice." (PMID 33542902, 2020). "Furthermore, the number of tumor foci in the KIF3B-shRNA group was much less than that in the control group." (PMID 33542902, 2020). "Moreover, the increased mRNA levels of KIF3B were also found in tumor tissues (P < 0.01)." (PMID 34422048, 2021). "BRMS1L, CPEB3, KIF3B, NEDD4L, PTPRJ, and RBL2 were significantly downregulated in tumor samples compared to controls." (PMID 40943553, 2025). "In contrast, tumors comprised of HEp3 cells that express Kif3b targeting shRNAs failed to reorganize the collagen fiber network at the primary tumor periphery." (PMID 29904055, 2018).
KIF3B also shares sentences with these, for which no sentence is quoted: oral squamous cell carcinoma (2 papers); ovarian carcinoma (2); pancreatic cancer (2); brain cancer (1); Dent disease (1); epidermoid-carcinoma (1); esophageal squamous cell carcinoma (1); genetic disease (1); head and neck cancer (1); infection (1); leukemia (1); lung carcinoma (1); melanoma (1); neurological disorders (1); polydactyly (1); psychosis (1); rectal cancer (1); renal carcinoma (1); renal Fanconi syndrome (1); Retinal atrophy (1); retinal degeneration (1); triple-negative breast carcinoma (1); Vertigo (1).